SOX11 (SRY-box transcription factor 11)
Diseases named in the same sentence as SOX11 in open-access papers (continued):
Sharing a sentence is not in itself a finding about the gene and the disease.
tumor (continued). "Third, we determined which of these genes showed significant correlation with SOX11 expression in 2 independent NB tumor cohorts (GSE8504717 and GSE4554718) and narrowed down the SOX11 early and late regulated gene list and established a SOX11 early (56 genes) and late (68 genes) gene signature." (PMID 36882421, 2023). "SOX11 was identified as the sole protein coding gene residing in the shortest region of overlap at 2 p distal to MYCN, suggesting a role as driver for selection of the respective amplicons during tumor formation." (PMID 36882421, 2023). "Lack of CD5 is seen in approximately 5–10% of cases and has been associated with better patient outcomes independent of favourable prognostic markers such as nnMCL, SOX11 negativity and low tumour cell proliferation." (PMID 36454275, 2023). "The CD70 locus was indeed identified as a direct target of SOX11, and could be induced thanks to CD40-L stimulation, part of the tumor B/TME interaction." (PMID 35804999, 2022). "In our study, SOX11 expression levels in ACC, COAD, ESCA, TGCT and UVM showed an increasing trend with increasing tumor stage, but the trend was more pronounced mainly in tumor stages I-III which might be due to the small sample size of stage IV patients." (PMID 36551589, 2022). "SOX11 also regulates CXCR4 expression, with CXCR4 being important for the tumor–TME interaction." (PMID 35804870, 2022). "Ki67+ cells were substantially more abundant in spheroids with reduced Sox11 levels, consistent with a role for Sox11 in keeping tumour cells in a non-proliferative state when expressed at higher levels." (PMID 33969421, 2021). "Higher levels of SOX11 in DCIS.com cells led to increased metastatic burden to the brain in xenograft studies, whereas in our current study, lower levels of Sox11 led to shortened tumour latency and increased metastatic burden, particularly to the liver." (PMID 33969421, 2021). "Potential downstream SOX11 targets identified by RNA sequencing of tumours formed after intraductal and fat pad injections of DCIS‐control and DCIS‐SOX11 cells; list of the top upregulated genes in DCIS‐SOX11 lesions from samples collected 6 weeks after intraductal mammary injection." (PMID 28707729, 2017). "Cases with negative lymph node status and early tumor invasion stage tended to have a higher SOX11 positive rate." (PMID 24604109, 2014). "Studies have shown that SOX2, SOX3, SOX4, SOX9 and SOX11 are upregulated and possess oncogenic functions in different types of cancers, while SOX1, SOX7, SOX11, SOX15 and SOX17 have been identified as tumor suppressors." (PMID 25301735, 2014). "Re-expression of SOX11 in EOC indicates a potential use of epigenetic drugs to affect cellular growth in SOX11-negative tumours." (PMID 21943380, 2011). "In particular, SOX11 is expressed in some subtypes of ALLs (TEL-AML1-positive or with E2A rearrangements), MCLs and part of the BL, but not in any of the other neoplasias analyzed, including the indolent variant of MCL." (PMID 21738649, 2011). "To address whether our whole transcriptome analysis results are in agreement with the previously published literature, we evaluated the expression levels of CCND1 and SOX11 mRNAs as well as ROR1-AS1 and LINK-A (LINC001139) lncRNA expression levels in MCL tumor tissue samples." (PMID 36359790, 2022). "In addition, SOX11 mediates the expression of platelet-derived growth factor alpha (PDGFA), focal adhesion kinase (FAK) and C-X-C motif chemokine receptor 4 (CXCR4), which promote angiogenesis, metastasis and tumor cell migration, respectively." (PMID 34256839, 2021). "Furthermore, we also showed that SOX11 promotes invasive transition of DCIS.com cells that were injected into the mammary duct to mimic formation of DCIS-like lesions within the mammary duct prior to progression to invasive state and tumour formation." (PMID 32909943, 2020).
tumor (continued). "Within each investigated tumor entity, SOX11 could be unmethylated with or without protein expression or show a varying degree of methylation reflecting a large degree of inter-tumor heterogeneity." (PMID 25880212, 2015). "Altogether, it is clear that the absence of SOX11 expression is tightly coupled to a methylated promoter in primary tumor samples, however no specific determinative CpG position could be identified as most alleles were either fully methylated or unmethylated." (PMID 20624318, 2010). "Furthermore, analysis of solid tumors revealed a strong nuclear expression of SOX11 in epithelial ovarian cancer (EOC), which correlated with a prolonged recurrence-free survival, suggesting a functional role for SOX11 in regulation of tumor growth." (PMID 20624318, 2010). "However, the expression of CCND2 or CCND3 without the presence of a detectable translocation, particularly in SOX11-negative tumours, should not be considered as evidence of MCL since B cell neoplasms express variable levels of CCND2 or CCND3 without translocations of these genes." (PMID 36454275, 2023). "Also, the discrepancies between the tumour size observed after xenografting iSOX11 cells via the mammary fat pad model and the MIND model, as well as the finding that EGF can decrease MEX3A levels, suggest an influence of microenvironmental factors on SOX11 tumour cell behaviour." (PMID 32909943, 2020). "Moreover, higher mRNA levels of SOX11 were detected in basal‐like and HER‐2 subtypes than those in luminal A and luminal B subtypes of BC, which implies that SOX11 could be an important marker that characterizes the ER‐negative tumor." (PMID 32043610, 2020). "The authors conclude that their results indicate that SOX11-negative MCL may be a particular subtype of this tumor characterized by more frequent morphological and immunophenotypic terminal B cell differentiation features that may be facilitated by the absence of SOX11 transcription factor." (PMID 26949423, 2016). "Both SOX11 and TPX2 showed a trend of increased expression levels with increasing tumor grade, whereas BCL11A did not." (PMID 23506684, 2013). "A key future direction is to explore if EGF/STAT3 signaling can ectopically induce SOX11 in non-tumorigenic cells, and if so, whether this prompts TWIST expression and a tumor-like phenotype." (PMID 41511366, 2026). "However, in SOX11− MCL cells, the low levels of PRDX2 are not able to manage oxidative stress generated during chemotherapy, and eventually tumor cells die upon treatments due to the increased lethal levels of ROS in SOX11− MCLs cells." (PMID 38570586, 2024). "Also in a more complex setting, using a single cell suspension derived from a tumor established by intravenous injection of Z138 MCL cells into NSG mice, SOX11-C1 was able to distinguish SOX11-positive from negative samples." (PMID 22738398, 2012).
cancer (87 papers, 2010 to 2026). A tumor composed of atypical neoplastic, often pleomorphic cells that invade other tissues. "In summary, our findings underline the multifaceted role and prognostic value of SOX11 in pan-cancer." (PMID 36551589, 2022). "In different cancers, a large number of mutations, amplifications and high mRNA levels were observed in SOX11." (PMID 36551589, 2022). "It was important to note that SOX11 amplification or mutation was uncommon in primary cancers, but SOX11 amplification and upregulation of expression were found in metastatic brain cancers, which was consistent with the results of our study." (PMID 36551589, 2022). "Regarding genetic alterations of SOX11 in pan-cancer, our data found that mutations were the most common type of genetic alteration of SOX11, followed by amplifications." (PMID 36551589, 2022). "First, we explored the association between SOX11 expression levels and stem cell scores in pan-cancer." (PMID 36551589, 2022). "The up‐regulation of SOX2, SOX4, SOX5, SOX8, SOX9 and SOX18 are found to be associated with poor outcome in different cancer types; however, the up‐regulation of SOX11 and SOX30 is favourable for the prognosis in other cancer types." (PMID 32363730, 2020). "Some of the LSA genes have been shown to be overexpressed in advanced cancers and be associated with unfavorable clinical outcomes such as SOX11, PTPRN, PNCK and HMGA2." (PMID 28427185, 2017). "Hypomethylation of oncogenic genes has been associated with many cancer types; and methylation has been shown to be associated with SOX11 expression in hematopoietic and solid tumors." (PMID 26894864, 2016). "Kaplan Meier estimates demonstrated an association between SOX11 nuclear expression and an improved cancer-specific survival in high grade EOC (p = 0.047)." (PMID 21943380, 2011). "Sox11 expression is associated with DNA methylation levels in some cancers." (PMID 39039706, 2024). "Furthermore, SOX9, SOX10, and SOX11 are associated with increased tumor metastasis and worse overall survival by regulating the ability of cancer cells to undergo EMT and acquire mesenchymal characteristics." (PMID 37444447, 2023). "As a result, aberrant expression of SOX11 has been implicated in 27 kinds of cancer types." (PMID 36551589, 2022). "Therefore, low expression of Sox11 may have an association with DNA methylation in cancer progression." (PMID 39039706, 2024). "The transcription factor SOX11, has a context-dependent role in cancer, and appears to be downregulated in late FDIM." (PMID 40683913, 2025). "The shared mechanisms of SOX11 in inflammation, tissue remodeling, and disease progression suggest it is a potential therapeutic target in inflammatory and cancer-related pathologies." (PMID 41567998, 2025). "SRY-box transcription factor 11 (SOX11) is a transcription factor that has recently been found to be a prognostic marker for certain cancers." (PMID 40804837, 2025). "The other four genes, COCH, CST9, SOX11, and TDGF1, as well as CHST4, have also been implicated in the immune-related GO term, indicating the importance of immunomodulatory mechanisms in cancer therapy." (PMID 38396947, 2024). "SRY‐box transcription factor 11 (Sox11) has been reported to serve as a prognostic marker for various cancers." (PMID 39039706, 2024). "Sox11 plays various interesting roles in development, bone remodeling, cancer, adult neurogenesis, and nerve regeneration." (PMID 38800035, 2024). "Multiple studies demonstrated that the aberrant expression of Sox11 is related to cancer progression and prognosis." (PMID 39039706, 2024). "Subsequently, IHC stains for xenograft tissue extracted from nude mice demonstrated that knock‐down within Sox11 can markedly downregulate Ki67, which is related to cancer growth." (PMID 39039706, 2024). "While Sox11 is thus a critical regulator of the onset and progression of cancer, its specific functional relevance in the progression of OLP to OSCC has yet to be established." (PMID 39039706, 2024).
cancer (continued). "Abnormal upregulation of SOX11 has been reported in various cancers; however, the prognostic implications of SOX11 expression appear to be contingent on the specific cancer type." (PMID 38534932, 2024). "High expression of Sox11 in various cancers is generally correlated with poor prognosis as it appears to support the epithelial-to-mesenchymal transition of cancer cells." (PMID 37705115, 2023). "The ex vivo expansion and manipulation of SOX11-specific T cells is a crucial step for developing effective cancer immunotherapy." (PMID 36768267, 2023). "Two years later, the same research group reported that the immunohistochemical expression of SOX11 accounts for the improved survival of patients with high-grade and especially endometrioid epithelial ovarian cancer, depending on cancer stage." (PMID 37760985, 2023). "We also explored the relationship between SOX11 expression and immune cell infiltration in pan-cancer." (PMID 36551589, 2022). "To reveal the role of SOX11 in pan-cancer, we systematically integrated multiple databases from the perspective of bioinformatics." (PMID 36551589, 2022). "We also verified the SOX11 protein level in cancer and corresponding normal tissues using the HPA database." (PMID 36551589, 2022). "Our work highlights the diverse role of SOX11 in different types of tumors, which points out several directions for future prospective studies on SOX11 in cancer." (PMID 36551589, 2022). "Previous studies have shown that promoter hypermethylation of SOX11 inhibits SOX11 expression in cancer cells." (PMID 35681050, 2022). "Our study also showed the correlations of SOX11 with the level of immune infiltration in various cancers." (PMID 36551589, 2022). "The main biological processes of SOX11 in cancers were analyzed by Gene Set Enrichment Analysis (GSEA)." (PMID 36551589, 2022). "Then RNA-seq data from the TCGA database were applied to analyze the expression of SOX11 in various cancers." (PMID 36551589, 2022). "SOX11 expression was also found in the cancer tissues of the thyroid (n = 2), esophagus (n = 3), colon (n = 6), rectum (n = 4), liver (n = 5), lung (n = 7) and breast (n = 4) tissues." (PMID 36551589, 2022). "As a downstream event of activated ESR1 signalling we detected markedly increased levels of the transcription factor SOX11 that has crucial role in embryonic development but is also induced in adults upon tissue injury and cancer." (PMID 35218417, 2022). "It seems that the mir-383/SOX11 axis affects the Wnt/β-catenin signaling pathway, thereby reducing its activation and further inducing apoptosis, inhibiting the viability of cancer cells and reducing tumorigenic capacity." (PMID 36313570, 2022). "SOX11 is a crucial member of the SOX transcription factors, which encodes a neural transcription factor, have functional role in multiple cancers." (PMID 35912006, 2022). "Accumulated evidence showed that SOX11 is overexpressed in most cancers, including mantle cell lymphoma, glioma, medulloblastoma, ovarian cancer, and breast cancer." (PMID 35267473, 2022). "Analysis of the correlation of survival and SOX11 expression using Kaplan–Meier plotter, PrognoScan, and R2 databases revealed significantly higher survival in the low SOX11 expression group of cancer patients than in the high expression group." (PMID 34442467, 2021). "Overexpression of SOX11 delays cancer progression by repressing the development of cancer-initiating cells and reducing cancer metastasis." (PMID 33536579, 2021). "EMT, stemness and plasticity are intertwined and SOX11 is well poised to function as a key regulator of epithelial/mesenchymal cell states during development and in cancers." (PMID 32909943, 2020). "The sex-determining region on the Y-chromosome-related high-mobility-group box (SOX) transcription factor 11 (SOX11) plays a key role in human development and differentiation and is frequently increased in various human cancers." (PMID 32586027, 2020).
cancer (continued). "Although SOX11 promotes cancer progression in HNSCC, the regulatory role of SOX11 in early oral/head and neck carcinogenesis remains inconclusive." (PMID 30922366, 2019). "Accumulating evidence shows that SOX11 is involved in the biological processes of many human cancers, whereas the impact of SOX11 on the progression of different cancers is still controversial and seems to be determined by cancer types." (PMID 31531526, 2019). "CircCEP128 and SOX11 had a positively related dependency both in cancer tissues and in adjacent normal tissues (P < 0.05)." (PMID 30134837, 2018). "For example, in the eight cancer types (BLCA, BRCA, COAD, KIRC, LIHC, LUAD, THCA and UCEC) with both stage phenotype information and normal control samples, SOX11 expression follows the pattern in four cancer types (BLCA, KIRC, LIHC and THCA)." (PMID 28427185, 2017). "Among these candidates, six genes (RhoGDI1, ALCAM, FOXJ2, FOXO3, NDRG2 and SOX11) were involved in the suppression of cancer metastasis." (PMID 26460549, 2015). "As SOX11 has shown to have a functional role and prognostic relevance in multiple cancer entities, we further investigated the potential to re-express SOX11 using epigenetic drugs." (PMID 25880212, 2015). "Sox11 is a member of the subgroup C family and has many interesting roles in development, cancer, nerve regeneration and adult neurogenesis." (PMID 26505998, 2015). "In hematopoietic malignancies, SOX11 knockdown and overexpression were found to be correlated with increased and decreased cell proliferation, respectively." (PMID 24604109, 2014). "As DNA methylation is the most widely studied epigenetic mechanism leading to deregulated gene expression in cancer, we initially analyzed the methylation status of SOX11 promoter by microarrays and bisulfite pyrosequencing." (PMID 21738649, 2011). "Furthermore, LINC01605 increased cancer cell proliferation, migration, invasion, and decreased apoptosis through the miR-3960/SOX11 axis." (PMID 41141624, 2025). "SOX11 expression exerts context-dependent effects on cancer cell survival, growth and metastasis." (PMID 36658220, 2023). "SOX11 is overexpressed in embryonic and cancer stem cells (CSC) of some tumors." (PMID 36509891, 2023). "The first were tightly regulated, through MELK, BRCA2, KIF14, BUB1, and TOP2A, by five TFs (NFE2L3, RUNX1, RUNX2, BHLHE40, and the aging cancer-specific SOX11), two LncRNAs (ST7OT1 and CDKN2BAS), and four miRNAs (miR-21-5p, miR-363-3p, miR-873-5p, and miR-138-1-3p)." (PMID 37191407, 2023). "On the contrary, SOX9, SOX10, and SOX11 are upregulated in basal-like BC, indicating that therapeutic strategies targeting these factors may be beneficial for this subtype of cancer, which currently lacks targeted therapy." (PMID 37444447, 2023). "Finally, our work also suggests several future directions for future prospective studies that focus on SOX11 in cancer." (PMID 36551589, 2022). "Recently, SOX11 research has shifted from embryogenesis to cancer development." (PMID 36551589, 2022). "SOX11 may play distinct roles in various types of cancer, so it shows an increase in some cancers and a decrease in others." (PMID 36313570, 2022). "Our study aimed to explore the various aspects of SOX11 in pan-cancer." (PMID 36551589, 2022). "SOX11 prevents the proliferation and invasion of cancer cells." (PMID 36313570, 2022). "However, we discovered that SOX11 expression was altered in 27 cancer tissues from the TCGA database compared to normal tissues." (PMID 36551589, 2022). "Aberrant SOX11 expression has been observed in many types of human malignant tumors." (PMID 36551589, 2022). "We found that SOX11 is low in cancer tissues of LUAD patients and is related to survival prognosis." (PMID 35033084, 2022). "Nevertheless, the roles of SOX11 in different cancer types remain controversial." (PMID 36551589, 2022). "The key pro-oncogenic role of SOX11 has also been demonstrated in various cancers." (PMID 35267473, 2022).